ATP10B (ATPase phospholipid transporting 10B (putative))
Description:
Catalytic component of a P4-ATPase flippase complex, which catalyzes the hydrolysis of ATP coupled to the transport of glucosylceramide (GlcCer) from the outer to the inner leaflet of lysosome membranes. Plays an important role in the maintenance of lysosome membrane integrity and function in cortical neurons.
Synonyms: ATPVB; KIAA0715; FLJ21477
Tractability: Antibody: UniProt predicts a signal peptide or a membrane-spanning region; its Gene Ontology location is reachable by antibodies, with medium confidence.
Gene: Protein-coding gene on chromosome 5 (160,563,120 to 160,852,214, reverse strand). Ensembl gene ENSG00000118322.
Subcellular location: Late endosome membrane; Lysosome membrane; Endoplasmic reticulum membrane
Pathways (Reactome):
Transport of small molecules: Ion transport by P-type ATPases
Gene Ontology:
Molecular function: ATPase-coupled intramembrane lipid transporter activity; glycosylceramide flippase activity; phosphatidylcholine flippase activity; protein binding; ATP binding; ATP hydrolysis activity; magnesium ion binding; nucleotide binding
Biological process: lysosomal membrane organization; phospholipid translocation; phospholipid transport
Cellular component: endoplasmic reticulum; endoplasmic reticulum membrane; late endosome membrane; lysosomal membrane; membrane; phospholipid-translocating ATPase complex
Genetic constraint (gnomAD): Loss-of-function variants: 114 observed, 138.16 expected, observed/expected ratio (o/e) 0.83, 90% interval 0.71 to 0.96. The upper end of that interval is the gene's LOEUF score, 0.96, which puts it in group 4 of 6, group 1 being the genes least tolerant of losing a copy. Missense variants: 1,738 observed, 1,807 expected, observed/expected ratio (o/e) 0.96, 90% interval 0.92 to 1. Synonymous variants: 643 observed, 689.43 expected, observed/expected ratio (o/e) 0.93, 90% interval 0.87 to 1.
Homologues: Orthologues: chimpanzee ATP10B (99% identical), macaque ATP10B (97% identical), dog ATP10B (86% identical), pig ATP10B (86% identical), rat Atp10b (84% identical), mouse Atp10b (84% identical), rabbit ATP10B (80% identical), guinea pig ATP10B (79% identical), tropical clawed frog atp10b (62% identical), zebrafish atp10b (47% identical), Drosophila melanogaster CG4301 (25% identical), Drosophila melanogaster CG9981 (22% identical), and 3 more. Paralogues in human: ATP10D (48% identical), ATP10A (47% identical), ATP8B1 (29% identical), ATP8B4 (28% identical), ATP8B2 (28% identical), ATP8A2 (28% identical), ATP8A1 (27% identical), ATP11A (26% identical), ATP11B (26% identical), ATP8B3 (26% identical), ATP11C (26% identical), ATP9B (22% identical), and 1 more.
Diseases named in the same sentence as ATP10B in open-access papers:
ATP10B is named in the same sentence as 7 diseases in open-access papers, as found by Europe PMC text mining. Sharing a sentence is not in itself a finding about the gene and the disease. The quoted sentences say what the papers report.
Parkinson disease (3 papers, 2020 to 2025). A progressive degenerative disorder of the central nervous system characterized by loss of dopamine producing neurons in the substantia nigra and the presence of Lewy bodies in the substantia nigra and locus coeruleus. "Recently, loss-of-function mutations in the ATP10B gene have been identified in Parkinson’s disease patients, pointing to ATP10B as a candidate genetic risk factor." (PMID 40676227, 2025). "Mutations in ATP10B, a GlcCer flippase that localizes to the endo-lysosomal system, were found in a cohort of Parkinson’s disease (PD) patients." (PMID 38382846, 2024). "To investigate the role of ATP10B in Parkinson’s disease neuropathology, specifically in the nigrostriatal dopaminergic system, we induced ATP10B knockdown specifically in substantia nigra pars compacta neurons of rats using viral vector technology." (PMID 40676227, 2025). "Moreover, a broader impact on the functionality of the nigrostriatal pathway was evidenced as rats with Atp10b knockdown exhibited motor impairments similar to those observed in Parkinson’s disease patients." (PMID 40676227, 2025).
melanoma (2 papers, 2020 to 2025). A malignant, usually aggressive tumor composed of atypical, neoplastic melanocytes. "Lysosomal functionality is compromised after ATP10B knockdown (KD) in WM-115 melanoma cells, as well as in primary cortical neurons with ATP10B KD, where the loss of ATP10B also increases susceptibility to cell death." (PMID 40676227, 2025). "Extensive screening of cell lines, including neuroblastoma cell lines, indicated sufficient endogenous ATP10B expression in the human adenocarcinoma Im95m and melanoma WM-115 cells." (PMID 32172343, 2020).
tumor (2 papers, 2017 to 2025). "However, the high E2F group presented increased frequencies of ABCA13, LRP1B, and ATP10B missense/nonsense mutations, suggesting a potential link between E2Fs and tumor-suppressor gene alterations." (PMID 40599792, 2025). "Four SNVs of NOTCH2, PDE4DIP, ATP10B and NSD1 and one frameshift INDEL of BAP1 were validated by Sanger sequencing on tumour RNA." (PMID 28484631, 2017).
ATP10B also shares sentences with these, for which no sentence is quoted: cancer (2 papers); adenocarcinoma (1); influenza (1); neuroblastoma (1).